PPIA (peptidylprolyl isomerase A)
Diseases named in the same sentence as PPIA in open-access papers (continued):
Sharing a sentence is not in itself a finding about the gene and the disease.
tumor (continued). "Furthermore, PPIA is involved in biological processes such as intracellular signaling, transcription, and apoptosis, therefore playing critical roles in microorganismal infections, inflammatory diseases, and tumor proliferation." (PMID 35840882, 2022). "However, only number of tumors showed significant correlation with expression of PPIAP22 or PPIA when we analyzed the correlation between expression of PPIAP22 or PPIA and clinicopathologic features, including gender, age, tumor size, number of tumors, metastasis, and TMN stages." (PMID 33790943, 2021). "While all proteins, as expected, were correlated with tumor stage according to proteomic data, GANAB, THIC/ACAT2, SEPT8, PPIA, and GALE showed an inverse correlation with tumor size, whereas MYDGF displayed a positive correlation." (PMID 41441336, 2025). "Based on these results, bioinformatics analysis provides a potential research direction regarding the interaction between Gal-3 tumor cells and stromal cells, which depends on two potential cell signaling pathways: CCL2-CCR2 and PPIA-BSG." (PMID 40600063, 2025). "To explore the clinical significance of PPIA and NRF2 in NSCLC, we examined their accumulation using a tumor tissue microarray comprising specimens of multiple diagnosed clinical stages." (PMID 38830868, 2024). "Differentially abundant proteins between tumor and healthy samples included PI3K, MAPK, BCL2, and PPIA proteins, which are involved in various biological pathways related to cell proliferation and growth." (PMID 39409902, 2024). "It revealed that all these five targets (GSN, ADAMTSL4, CALR, PPIA and TXN) can be secreted by the NPC 6-10B and 5-8F cells, which provided an important basis for our following studies to identify the serum tumor biomarkers of NPC." (PMID 28107202, 2017). "Among malignant samples, the expression of reference genes was substantially equivalent among tumor grade groups for ACTB, PPIA and TBP." (PMID 25473950, 2014). "Finally, PPIA and PRDX1 were both detected and overexpressed in tumor-derived extracellular vesicles." (PMID 38252632, 2024). "And PANX1, PPIA and TLR2 were highly expressed in tumor group." (PMID 37259066, 2023). "Additionally, in CD16 monocytes, the remaining NPA genes, JAK3, PPIA, and TLR4 were up-regulated in tumor tissues, while IFNGR1 was down-regulated in tumor samples." (PMID 38149248, 2023). "Furthermore, in this study, we demonstrated that SLC25A5, PPIA, and TNFRSF10B were correlated with tumor immune microenvironment infiltration and may be potential prognostic biomarkers for ESCA." (PMID 35840882, 2022). "Overall, The data show us that Keap1, Nrf2, PPIA, Prdx6 and CD147 were not correlated with tumor stage (T1 to T3), lymph node status (N0 to N1), pathological grade (GI to GIII) (P>0.05)." (PMID 24386210, 2013).
neurodegenerative disease (6 papers, 2013 to 2025). A disorder of the central nervous system characterized by gradual and progressive loss of neural tissue and neurologic function. "A comparison between plasma EV from a large cohort of ALS patients and other neurodegenerative diseases and controls showed that EVs contained known markers of ALS such as HSP90, PPIA or cyclophilin A and TDP-43." (PMID 37670049, 2023). "For this study, we chose two reference genes, PPIA and RPL13, which are relatively stable in the cerebral cortex across many neurodegenerative diseases." (PMID 36129947, 2022).
PPIA also shares sentences with these, for which no sentence is quoted: cardiovascular diseases (26 papers); rheumatoid arthritis (18); COVID-19 (17); melanoma (12); coronary artery disease (9); cardiac hypertrophy (8); glioblastoma (8); heart failure (8); Hypertension (8); kidney disease (8); small cell lung carcinoma (8); myocardial infarction (7); Arthritis (6); cognitive decline (6); Cognitive impairment (6); diabetes (6); brain injury (5); diabetic nephropathy (5); myocarditis (5); periodontitis (5); type 2 diabetes (5); abdominal aortic aneurysm (4); acute kidney injury (4); aortic aneurysm (4); asthma (4); inflammation (4); injury (4); ischemia (4); liver fibrosis (4); Myocardial fibrosis (4).
A further 155 diseases each share a sentence with PPIA in 4 papers or fewer.